RNU7-25P (RNA, U7 small nuclear 25 pseudogene)
Synonyms: U7.25
Gene: Small nuclear RNA gene on chromosome 18 (3,093,568 to 3,093,629, forward strand). Ensembl gene ENSG00000252353.
Homologues: Orthologues: chimpanzee U7 (98% identical). Paralogues in human: RNU7-11P (94% identical), RNU7-3P (92% identical), RNU7-13P (90% identical), RNU7-2P (90% identical), RNU7-41P (90% identical), RNU7-47P (90% identical), RNU7-22P (89% identical), RNU7-27P (89% identical), RNU7-40P (89% identical), RNU7-4P (89% identical), RNU7-61P (89% identical), RNU7-6P (89% identical), and 143 more.